CCR9 (C-C motif chemokine receptor 9)
Description:
Receptor for chemokine SCYA25/TECK. Subsequently transduces a signal by increasing the intracellular calcium ions level. (Microbial infection) Alternative coreceptor with CD4 for HIV-1 infection.
Synonyms: CC-CKR-9; CDw199; GPR28; GPR-9-6
Tractability: Small molecule: a drug acting on it is in phase 2 or 3 trials; a structure with a bound ligand is known; a high-quality ligand is known; it belongs to a druggable protein family. Antibody: UniProt places it where antibodies can reach, with high confidence; its Gene Ontology location is reachable by antibodies, with high confidence; UniProt predicts a signal peptide or a membrane-spanning region; the Human Protein Atlas places it where antibodies can reach. PROTAC: a small molecule that binds it is known.
Target class: Chemokine receptor; Peptide receptor (family A GPCR); Family A G protein-coupled receptor; CC chemokine receptor; Membrane receptor
Gene: Protein-coding gene on chromosome 3 (45,884,425 to 45,904,311, forward strand). Ensembl gene ENSG00000173585.
Subcellular location: Cell membrane
Subcellular location (Human Protein Atlas): Plasma membrane; Endoplasmic reticulum
Pathways (Reactome):
Signal Transduction: Chemokine receptors bind chemokines; G alpha (i) signalling events
Gene Ontology:
Molecular function: C-C chemokine binding; C-C chemokine receptor activity; chemokine receptor activity; G protein-coupled receptor activity
Biological process: calcium-mediated signaling; cell chemotaxis; cellular defense response; chemotaxis; G protein-coupled receptor signaling pathway; immune response; positive regulation of cytosolic calcium ion concentration; chemokine-mediated signaling pathway
Cellular component: cell surface; external side of plasma membrane; plasma membrane; membrane
Genetic constraint (gnomAD): Loss-of-function variants: 4 observed, 9.27 expected, observed/expected ratio (o/e) 0.43, 90% interval 0.21 to 0.99. That is too few expected variants to judge how well the gene tolerates losing a copy. Missense variants: 394 observed, 478.14 expected, observed/expected ratio (o/e) 0.82, 90% interval 0.76 to 0.9. Synonymous variants: 159 observed, 179.38 expected, observed/expected ratio (o/e) 0.89, 90% interval 0.78 to 1.01.
Homologues: Orthologues: chimpanzee CCR9 (100% identical), macaque CCR9 (99% identical), pig CCR9 (91% identical), rabbit CCR9 (86% identical), rat Ccr9 (86% identical), mouse Ccr9 (86% identical), dog CCR9 (85% identical), guinea pig CCR9 (74% identical), zebrafish ccr9a (43% identical), zebrafish ccr9b (40% identical). Paralogues in human: CCR7 (40% identical), CCR6 (34% identical), ACKR4 (33% identical), CCR5 (33% identical), CXCR2 (32% identical), CCR10 (32% identical), CCR4 (32% identical), CXCR1 (32% identical), CXCR6 (32% identical), CCR1 (31% identical), CCR3 (31% identical), CCR2 (31% identical), and 11 more.
Diseases named in the same sentence as CCR9 in open-access papers:
CCR9 is named in the same sentence as 140 diseases in open-access papers, as found by Europe PMC text mining. Sharing a sentence is not in itself a finding about the gene and the disease. The quoted sentences say what the papers report.
COVID-19 (42 papers, 2020 to 2025). A disease caused by infection with severe acute respiratory syndrome coronavirus 2. "We did not observe changes in the expression of any of the six genes clustered in the locus associated with respiratory failure in patients with COVID-19 (CCR9, SLC6A20, LZTFL1, CXCR6, XCR1, FYCO1)." (PMID 40722786, 2025). "This QTL shows conserved synteny with a locus in humans on Chr3 (which includes Ccr9 and Cxcr6) that was identified in COVID-19 human Genome-wide Association Studies (GWAS) predicting severe outcome and hospitalization." (PMID 35862771, 2022). "In this regard, a gene cluster on chromosome 3 containing CCR1, CCR3, CXCR6, and CCR9, has been identified as a major risk factor for COVID-19 at the genome-wide level (Zeberg and Pääbo, 2020)." (PMID 36320810, 2022). "In total, several GWAS in humans have identified a common locus on Chr3 (3p21.31), that identified six genes associated with COVID-19 severity, susceptibility, respiratory failure, and risk of hospitalization and included CCR9 and CXCR6 (14, 15, 32, –, 34)." (PMID 35862771, 2022). "In naive regulatory T cells, TWAS found a significant association between COVID-19 severity and CCR9, which encodes for the gut-homing chemokine receptor CCR947." (PMID 34799557, 2021). "Notably, four chemokine receptors identified by our study (CXCR6 in the ileum, CCR1/2 and CCR9 in both ileum and colon) are coded in a genomic region found to be a COVID-19 risk locus on chromosome 3, further validating our predictions." (PMID 35501398, 2022). "While the fraction of CD4+ memory T cells expressing the chemokine receptor CCR9, which is associated with trafficking to the small intestine, was similar between patients with COVID-19 and healthy controls, their absolute numbers in the circulation were significantly reduced." (PMID 33959123, 2021). "A severe COVID-19 GWAS Group has identified genetic variants linked to genes such as SLC6A20, LZTFL1, CCR9, FYCO1, CXCR6, and XCR1 in patients experiencing respiratory failure due to COVID-19." (PMID 40143318, 2025). "A recent study developed by our research group investigated genetic variants present in the genes SLC6A20, LZTFL1, CCR9, FYCO1, CXCR6, XR1 and ABO involved with the severity of COVID-19 in indigenous people." (PMID 38543725, 2024). "The first and most significant locus described in GWAS associated with COVID-19 critical is 3p21.31, which encompasses six genes (SLC6A20, LZTFL1, CCR9, FYCO1, CXCR6, and XCR1) (The Severe COVID-19 GWAS Group, 2020)." (PMID 38226654, 2024). "A gene-based association test revealed a significant association in BAZ2B and in previously known COVID-19 risk loci: LZTFL1, XCR1, FYCO1, CCR9, and IFNAR2." (PMID 39361370, 2024). "Of these genes, 7 are chemokine receptor genes (CCR1, CCR2, CCR3, CCR5, CCR9, CCRL2, and CXCR6), which are likely linked to the segment’s association with COVID-19 severity." (PMID 36763080, 2023). "Irinotecan is a topoisomerase I inhibitor that binds to CCR9 protein (binding affinity: −17.1 kcal/mol) and has also been suggested as a potential candidate therapy to counter cytokine storms in critically ill COVID-19 patients." (PMID 37886583, 2023). "Through COVID-19-relevant transcriptome and enrichment gene sets, seven druggable targets with COVID-19-relevant functions were identified, including CCR9, CXCR6, XCR1, IL10RB, OAS1, OAS2, and OAS3." (PMID 37886583, 2023). "We found six genes at locus 3p21.31 significantly associated with severe COVID-19: LZTFL1, FYCO1, XCR1, CCR9, TMLHE-AS1, and SCYL2." (PMID 37547597, 2023). "We found significant associations between COVID-19 and LZTFL1, FYCO1, XCR1, CCR9, TMLHE-AS1, and SCYL2 at 3p21.31." (PMID 37547597, 2023). "Vδ2Vγ9T cell clusters 20 and 25 from CR2 panel were expanded in severe and critical COVID-19 (Bonferroni-adjusted P-value range 0.00564–6.39 × 10−8) and characterized by CCR9, CXCR3 and TIGIT expression." (PMID 36433939, 2022).
COVID-19 (continued). "We discovered several chemokine receptor signatures on NK cells (N = 8) associated with the development of severe COVID-19, including upregulated CX3CR1 expression on early NK cells and increased levels of CCR4, CCR9 and CXCR3 on terminal NK cells." (PMID 36433939, 2022). "This study aimed to associate genetic variants in the SLC6A20, LZTFL1, CCR9, FYCO1, CXCR6, XCR1, and ABO genes with the risk of severe forms of COVID-19 in Amazonian Native Americans, and to compare the frequencies with continental populations." (PMID 35455670, 2022). "We identified putative causal genes, including SLC6A20, CXCR6, CCR9, and CCR5 in the locus on 3p21.31, quantifying their effect on mediating expression and on severe COVID-19." (PMID 35318325, 2022). "The first COVID-19 genome-wide association study identified the 3p21.31 gene cluster, including “SLC6A20, LZTFL1, CCR9, FYCO1, CXCR6, and XCR1” as a genetic susceptibility locus in severe patients with COVID-19 and respiratory failure." (PMID 37521836, 2022). "Two loci associated with respiratory failure in COVID-19 were found, one of which was the GA-G insertion-deletion variant in locus 3p21.31 that is composed of six genes (SLC6A20, LZTFL1, CCR9, FYCO1, CXCR6, and XCR1)." (PMID 33791232, 2021). "Two of these genes, CCR9 and CXCR6, were also found within the set of COVID-19 associated genes, while CCR5 and PIGN genes were novel." (PMID 34557504, 2021). "The CCR9 gene (MIM: 604738) encodes a chemokine receptor that plays an essential role in the mucosal immune system and has been associated with increased COVID-19 outcome severity, especially in Europeans." (PMID 39975073, 2025). "Also, recently, it was found that a region of our DNA situated on chromosome 3 (locus 3p21.31), spanning a length of 49.3 kb, consisting of 6 genes (SLC6A20, LZTFL1, CCR9, FYCO1, CXCR6, and XCR1), was associated with the risk of developing severe COVID-19." (PMID 37929242, 2023). "Six genes (namely, SLC20A6, CCR9, CXCR6, CCR2, CCR5, and CCR5AS) were significant from the MR-JTI analysis after Bonferroni correction, indicating causal support for these genes on COVID-19 hospitalization." (PMID 35318325, 2022). "The present study investigated genetic variants in the SLC6A20, LZTFL1, CCR9, FYCO1, CXCR6, XCR1, and ABO genes that are potentially related to severe forms of COVID-19 in Amazonian Native American populations, and compared their frequencies with continental populations." (PMID 35455670, 2022). "The first GWAS analysis with 1980 patients with COVID-19 identified two loci associated with the most severe forms of COVID-19: one locus was 3p21.31, which includes the genes SLC6A20, LZTFL1, CCR9, FYCO1, CXCR6, and XCR1, while the other was 9q34.21, including the ABO blood group." (PMID 35455670, 2022). "This locus contained six genes (SL6A20, LTZFL1, CCR9, FYCO1, CXCR6 and CXR1) that could all plausibly be linked to COVID-19 pathophysiology on the basis of their known functions." (PMID 33339864, 2020). "The strongest and most consistent finding for COVID-19 severity is the 3p21.31 region containing multiple protein-coding genes, including LZTFL1, SLC6A20, FYCO1, and chemokine receptor genes (CCR9, CXCR6 and XCR1)." (PMID 38517939, 2024). "Moreover, CCR1 was reported to be expressed by CD16+ monocytes, while CCR5, CCR9, and CXCR6 by T cell subsets in COVID-19 patients." (PMID 39811276, 2025). "Chemokine receptors, such as CCR9, CXCR6, CCR1, CCR3, CCR5, and CCR2, are all located on chromosome 3 and already showed significant associations with COVID-19 without network boosting." (PMID 36291657, 2022). "Finally, two GWAS have identified the loci 3p21.31 (LZTFL1, SLC6A20, CCR9, FYCO1, CXCR6, and XCR1) and 9q34.2 (ABO) with COVID-19 severity." (PMID 33868239, 2021).
COVID-19 (continued). "deleted this portion of LZTFL1 using a genome editor CRISPR/Cas9 in blood cell lines and found that the expression of CCR9 and SLC6A20 was affected by the locus, suggesting that this COVID-19 GWAS locus at chromosome locus 3p21.21 may influence different genes depending on cell type." (PMID 34998241, 2022). "We also found differences in the expression of homing markers on PBs from COVID-19 patients compared to that in healthy controls, with integrin β1 and CCR10 but not CCR9 being expressed on the cells." (PMID 37071584, 2023).
colitis (30 papers, 2011 to 2025). Inflammation of the colon. "To understand the role of CCR9 in the CRC development, we first established the colitis-associated colorectal cancer model, using CCR9+/− and CCR9−/− mice administering AOM/DSS." (PMID 40305493, 2025). "In this regard, it has been published with regards to murine models, that CCR9−/− mice are more susceptible to DSS-induced colitis." (PMID 36009431, 2022). "Consistently, when we transferred microbiota antigen-specific T cells from CBir1 Tg mice into Rag-/- mice, CCR9-deficient T cells were able to induce equally severe of colitis when compared to that induced by WT T cells." (PMID 26230654, 2015). "Colitis was induced by adoptive transfer of CD4+ T lymphocytes isolated from either WT CBir1Tg or CCR9-/- CBir1 Tg mice into T cell-deficient TCRβδ-/- mice." (PMID 26230654, 2015). "We used a murine model of oxazolone-induced colitis to investigate the potential regulatory roles of CCL25/CCR9 interactions in NKT cells and the underlying mechanisms involved." (PMID 24936795, 2014). "While certain therapeutic approaches have focussed on blocking gut homing receptors for amelioration of colitis, it has also been shown that CCR9 deficiency exacerbates colitis due to impairment of Treg recruitment to the gut." (PMID 23704880, 2013). "The delayed recovery from acute colitis is further characterized by an accumulation of pDCs and a change of the pDC/cDC ratio in the gut-associated lymphoid tissue in CCR9−/− mice." (PMID 21283540, 2011). "The most compelling argument for a physiologic role of CCL25/CCR9 interactions during an inflammatory response in the colon is derived from the increased susceptibility to colitis and the high mortality rate observed in CCR9−/− animals." (PMID 21283540, 2011). "We next analyzed how the increased susceptibility to DSS colitis affects IBD symptoms in CCR9−/− animals." (PMID 21283540, 2011). "CCR9−/− mice are more susceptible to DSS colitis than WT littermate controls as shown by higher mortality, increased IBD score and delayed recovery." (PMID 21283540, 2011). "Specifically, their results showed that CCR9-knockout mice were more susceptible to DSS-induced colitis compared to wild-type controls, and that a dysregulated Th-17 immune response involving different macrophage subsets was observed during their recovery period following DSS treatment." (PMID 38667916, 2024). "However, the D5R deficiency and CCR9 deficiency in CD4+ T-cells reduced the development of colitis in a similar manner." (PMID 34884737, 2021). "Moreover, CCL25 expression in the colon is associated with high frequencies of CCR9+ tissue-infiltrating effector T-cells in patients with colitis, which exhibit increased potential toward adhesion to liver endothelium." (PMID 26873648, 2016). "This study investigates the potential role of CCR9 in the recruitment of immune cells known to be crucial during CRC progression (CD8+ T cells versus Tregs), using the Colitis-Associated Colorectal Cancer mice model." (PMID 40305493, 2025). "In the colon of colitis mice, the mRNA levels of Itgα4 (integrin subunit alpha 4), Itgβ7 (integrin subunit beta 7), and Ccr9 (C-C motif chemokine receptor 9) were all reduced compared with the healthy controls." (PMID 35889745, 2022). "Although CCR9–/– T cells traffic to the colon and induce severe colitis similar to WT T cells, naive WT T cells induce more severe disease in recipient animals devoid of CCL25 expression." (PMID 34490243, 2021). "Nonetheless, the mechanism of CCR9+ DC regulation by ILCs in the intestine during colitis remains a stone unturned and requires further investigation." (PMID 33123124, 2020). "For example, the orally active, small molecule inhibitor CCX282-B, which targets CCR9, has shown efficacy in a colitis model in animals, as well as promising results in clinical trials against colitis." (PMID 28974038, 2017).
colitis (continued). "This is important as the CCR9/CCL25 pathway is being targeted to treat inflammatory bowel disease (IBD) and evidence of upregulation in active colitis would support clinical studies of anti-CCR9 therapy." (PMID 26873648, 2016). "We not only detected elevated frequencies of CCR9+ T-cells in active macroscopic colitis but also saw high (albeit relatively fewer) numbers in microscopic colitis." (PMID 26873648, 2016). "Considering that blockade of CCR9 attenuates early intestinal inflammation, we first sought to examine the role of CCR9 in the pathogenesis of T cell-mediated colitis by using the CBir1-specific adoptive transfer model." (PMID 26230654, 2015). "The role of CCR9 in the initiation and progression of colitis was tested by pharmacological CCR9 inhibition with two small molecule antagonists, CCX282-B and CCX025." (PMID 26457007, 2015). "CCL25-/- Rag-/- mice developed more severe disease compared to that in WT Rag-/- mice on transfer of CD45RBhi T cells, possibly meaning that innate CCR9 expression also regulates colitis development." (PMID 26230654, 2015). "In a DSS-induced colitis model, CCR9-/- mice developed more severe colitis compared to that in WT mice upon insults with DSS." (PMID 26230654, 2015). "Collectively, our data indicate that, in addition to acting as a gut-homing molecule, CCR9 inhibits the Treg polarization, thereby contributing to its role in colitis development." (PMID 26230654, 2015). "The results presented herein clearly demonstrate that pharmacological inhibition of CCR9 provides a therapeutic benefit in the mdr1a−/− mouse colitis model." (PMID 26457007, 2015). "In studying the role of CCR9 in microbiota-reactive, T cell-mediated colitis, we unexpectedly demonstrated that CCR9 can inhibit Treg cell development." (PMID 26230654, 2015). "Treatment of mdr1a−/− mice with the CCR9 antagonist CCX025 resulted in complete protection from the development of colitis." (PMID 26457007, 2015). "We demonstrated significantly increased CCR9 expression on iNKT cells, an expanded iNKT population and increased chemotaxis of iNKT cells during oxazolone-induced colitis." (PMID 24936795, 2014). "And, the mRNA expression levels of NK1.1, CCL25 and CCR9 were increased in oxazolone-induced colitis in mice." (PMID 24936795, 2014). "We found that the expressions of NK1.1, CCL25 and CCR9 were significantly increased during oxazolone-induced colitis." (PMID 24936795, 2014). "In the present study, we evaluated the role of CCL25/CCR9 interactions in the regulation of NKT cells in a model of oxazolone-induced colitis." (PMID 24936795, 2014). "Since similar results were obtained with the CCL25−/− strain, these data show that the exacerbated colitis is a consequence of impaired CCL25/CCR9 interaction." (PMID 21283540, 2011). "The results presented in this study identify a novel role of CCL25/CCR9 interactions in the pathogenesis of a well-established acute colitis model mediated by oral administration of DSS." (PMID 21283540, 2011). "However, in the lungs of DSS-induced colitis mice both α4β7+ and CCR9 + CD4 + cells were significantly upregulated in the lung tissues (31.5% vs 1.4%; P < 0.001)." (PMID 40435188, 2025). "CCR9–/– and CCL25–/– mice are more susceptible to acute DSS colitis than WT controls." (PMID 34490243, 2021). "However, Ccr9-/- or Ccl25-/- mice show increased severity of dextran sodium sulfate (DSS)-induced colitis." (PMID 33123124, 2020). "If CCL25 expression is driven by colitis activity, and colonic CCR9+ T-cells are responsible for driving hepatobiliary inflammation in PSC, then it should follow that the risk of PSC increases with intestinal activity; an observation which does not hold true clinically." (PMID 26873648, 2016).